GDI2 (GDP dissociation inhibitor 2)
Description:
GDP-dissociation inhibitor preventing the GDP to GTP exchange of most Rab proteins. By keeping these small GTPases in their inactive GDP-bound form regulates intracellular membrane trafficking. Negatively regulates protein transport to the cilium and ciliogenesis through the inhibition of RAB8A.
Synonyms: RABGDIB; HEL-S-46e
Tractability: Antibody: its Gene Ontology location is reachable by antibodies, with high confidence; UniProt places it where antibodies can reach, with medium confidence. PROTAC: ubiquitination databases record sites on it; its protein half-life has been measured.
Gene: Protein-coding gene on chromosome 10 (5,765,221 to 5,842,132, reverse strand). Ensembl gene ENSG00000057608.
Subcellular location: Cytoplasm; Membrane; Golgi apparatus, trans-Golgi network
Subcellular location (Human Protein Atlas): Cytosol; Plasma membrane
Pathways (Reactome):
Immune System: Neutrophil degranulation
Vesicle-mediated transport: RAB GEFs exchange GTP for GDP on RABs
Gene Ontology:
Molecular function: protein binding; RNA binding; Rab GDP-dissociation inhibitor activity; GDP-dissociation inhibitor activity; GTPase activator activity; small GTPase binding
Biological process: negative regulation of cilium assembly; negative regulation of protein localization to cilium; signal transduction; vesicle-mediated transport; protein transport; regulation of protein localization; small GTPase-mediated signal transduction
Cellular component: cytosol; extracellular exosome; focal adhesion; vesicle; azurophil granule lumen; cytoplasm; extracellular region; secretory granule lumen; Golgi apparatus; membrane; synapse
Genetic constraint (gnomAD): Loss-of-function variants: 5 observed, 13.57 expected, observed/expected ratio (o/e) 0.37, 90% interval 0.19 to 0.77. The upper end of that interval is the gene's LOEUF score, 0.77, which puts it in group 3 of 6, group 1 being the genes least tolerant of losing a copy. Missense variants: 123 observed, 149.36 expected, observed/expected ratio (o/e) 0.82, 90% interval 0.71 to 0.96. Synonymous variants: 45 observed, 52.74 expected, observed/expected ratio (o/e) 0.85, 90% interval 0.67 to 1.09.
Homologues: Orthologues: chimpanzee GDI2 (99% identical), macaque GDI2 (99% identical), dog GDI2 (98% identical), pig GDI2 (97% identical), mouse Gdi2 (96% identical), rat Gdi2 (96% identical), guinea pig GDI2 (92% identical), tropical clawed frog gdi2 (90% identical), zebrafish gdi2 (89% identical), Drosophila melanogaster Gdi (67% identical), Caenorhabditis elegans gdi-1 (66% identical). Paralogues in human: GDI1 (86% identical), CHM (27% identical), CHML (27% identical).
Diseases named in the same sentence as GDI2 in open-access papers:
GDI2 is named in the same sentence as 36 diseases in open-access papers, as found by Europe PMC text mining. Sharing a sentence is not in itself a finding about the gene and the disease. The quoted sentences say what the papers report.
breast carcinoma (10 papers, 2015 to 2025). "We have identified their association with specific breast cancer subtypes and demonstrated the potential prognostic significance of ITGB6 and GDI2 in HER2+ breast cancer." (PMID 39630893, 2024). "As a regulator of GDP-GTP exchange reaction, GDI2 was reported to participate in various biological processes of solid tumors, such as breast cancer (BC), pancreatic carcinoma (PC), gastric cancer (GC), and so on." (PMID 34894398, 2021). "While in breast cancer (BC), GDI2 was found to contribute to EGFR endocytosis and thus enhance EGFR signaling and metastasis formation." (PMID 34894398, 2021). "Thus, the RAB5/RAB7A/GDI2 subnetwork regulates αVβ6-HER2 cross-talk to drive breast cancer invasion but is subverted in trastuzumab-resistant cells to drive αVβ6-independent and HER2-independent tumor progression." (PMID 39630893, 2024). "RHO GDI2 has been shown to be a metastasis suppressor in bladder and breast cancers." (PMID 25751262, 2015). "Consistent with the mechanistic data linking these molecules functionally, these analyses demonstrate that ITGB6, GDI2, and RAB5A expression positively correlate in patients with HER2+ breast cancer." (PMID 39630893, 2024). "Together, these findings lead to a model whereby GDI2 exerts a regulatory and suppressive effect in HER2+ breast cancer cells, limiting activation of RAB5 and constraining αVβ6-dependent HER2 trafficking, signaling, and invasion." (PMID 39630893, 2024). "Our MS data revealed that GDI2, a Rab-specific regulatory molecule, is recruited to αVβ6 IACs in HER2+ breast cancer cells." (PMID 39630893, 2024). "For instance, one study performed MR analysis on a single cohort of 732 plasma proteins, where GDI2 and CTSF were identified as potential targets for breast cancer, aligning with our research." (PMID 38304232, 2023). "The nominally significant SNPs included colorectal cancer GWAS SNPs in SMAD7, C11orf93, SCG5, and ATF1, and breast cancer SNPs related to CDKN2B-AS1, FGFR2, GDI2, CDYL2." (PMID 29698419, 2018). "Some of the screened proteins, like RPS3, GDI2, IARS2, were less investigated and their cancer-related mechanism and roles remain unclear in breast cancers." (PMID 33194682, 2020). "Similarly, GDI2 (OR: 0.85, 95% CI 0.80–0.91), ISLR2 (OR: 0.87, 95% CI 0.82–0.93), and CTSF (OR: 1.14, 95% CI 1.08–1.21) could potentially be targets for breast cancer." (PMID 37735436, 2023). "It was shown that GDI2 significantly expressed in most of the 33 kinds of solid tumors, such as hepatocellular carcinoma (LIHC, HCC), lung adenocarcinoma (LUAD), cholangiocarcinoma (CHOL), breast cancer (BRCA), glioblastoma (GBM), endometrial carcinoma of uterus (UCEC), etc." (PMID 34894398, 2021).
hepatocellular carcinoma (7 papers, 2021 to 2026). A malignant tumor that arises from hepatocytes. "GDI2 expression is associated with the diagnosis and prognosis of hepatocellular carcinoma, and its signaling is involved in lipid metabolism, extracellular matrix-building pathways, and the tumor microenvironment." (PMID 38431573, 2024). "A study suggested that GDI2 is associated with aggressive features and poor patient survival in hepatocellular carcinoma." (PMID 38304232, 2023). "GDI2 is highly expressed and closely associated with the occurrence and development of many tumors, making it a potential diagnostic and prognostic biomarker for hepatocellular carcinoma." (PMID 38420434, 2024). "The differential expression of GDI2 in gastric and hepatocellular carcinoma tissues provides potential insights for identifying biomarkers, predicting diagnosis, and assessing prognosis in gastric and hepatocellular carcinoma patients." (PMID 39323841, 2024). "Both qRT-PCR and western blot assays confirmed that compared with normal hepatic cells L02, GDI2 expression was increased in most of hepatoma cells." (PMID 34894398, 2021). "HPA analysis of protein expression showed that PRDX6, GCLM, HTATIP2, NOL10, KIF18A, RAP2A and GDI2 were highly expressed in the hepatocellular carcinoma tissues compared with normal control tissues." (PMID 34760691, 2021). "The only report studied in hepatic carcinoma cells HepG2 was to demonstrate that the methanol extract of T. indica fruit pulp altered the release of GDI2 from HepG2 cells, which possibly correlated GDI2 gene to cellular lipid metabolism." (PMID 34894398, 2021). "Then the differential expression of GDI2 was verified between two normal hepatic cell lines (L02, WRL-68) and seven hepatoma cell lines (Huh7, SK-HEP1, BEL-7402, PLC/PRF/5, SMMC-7721, HepG2, Hep3B) in vitro." (PMID 34894398, 2021).
prostate carcinoma (4 papers, 2021 to 2024). A carcinoma that arises from epithelial cells of the prostate gland. "In recent studies in prostate cancer, GDI2 expression was found to be upregulated in prostate cancer cells and tissues." (PMID 39323841, 2024). "Additionally, GDI2 is a target of paclitaxel through the p75NTR signaling pathway in prostate cancer tumorigenesis." (PMID 38420434, 2024). "In addition, they performed mediation analysis and confirmed that some proteins, PARP1, GDI2, and TMEM106A, exerted indirect effects on some diseases, such as prostate cancer, uterine leiomyoma, and idiopathic pulmonary fibrosis through telomere length." (PMID 38431573, 2024).
bladder cancer (3 papers, 2014 to 2024). "In pancreatic cancer the upregulation of GDI2 correlated with invasiveness, whereas in bladder cancer the downregulation of GDI2 was associated with a metastatic phenotype." (PMID 31248017, 2019). "GDI2 has also been identified as a suppressor of bladder cancer metastasis." (PMID 39831280, 2024). "Reduced expression of GDI2 is associated with decreased survival of bladder cancer patients; Restoring GDI2 expression has been shown to suppress metastasis without affecting primary tumor growth in animal models or growth in culture." (PMID 39831280, 2024). "In bladder cancer, the expression of Rho GDP dissociation inhibitor (GDI) β (GDI2) is diminished in cells with higher motility indicating a possible role as suppressor of migration." (PMID 24736611, 2014).
gastric cancer (3 papers, 2013 to 2022). A primary or metastatic malignant neoplasm involving the stomach. "Previously, we identified 14 downregulated proteins in RhoGDI2-overexpressing SNU-484(GDI2-4) gastric cancer cells compared with control SNU-484(Mock) cells by using comparative 2-DE." (PMID 24185104, 2013). "Moreover, GDI2 was differentially expressed in the secretome of esophageal squamous cell carcinoma (ESCC) as well as in gastric cancer (GC)." (PMID 34894398, 2021). "To determine whether Trio is critical for Rac1 activation in gastric cancer cells, we depleted Trio expression in SNU484/GDI2 and MKN28 cells, which led to marked reduction of Rac1 activity in these cells." (PMID 35008419, 2022).
colorectal cancer (2 papers, 2018 to 2024). A primary or metastatic malignant neoplasm that affects the colon or rectum. "The differences in the expression levels of GDI2 in normal colorectal tissues and tumor tissues of colorectal cancer (CRC) patients were detected." (PMID 39323841, 2024).
Down syndrome (2 papers, 2016 to 2020). "Moreover, both GDI2 (GDP dissociation inhibitor 2) and C21orf33 (chromosome 21 open reading frame 33) was dysregulated in fetal Down syndrome brain." (PMID 27100869, 2016).
medulloblastoma (2 papers, 2014 to 2021). A malignant, invasive embryonal neoplasm arising from the cerebellum. "Extrapolation of our cell culture results to the in vivo growth of medulloblastoma supports a mechanistic scheme whereby Arnt and Gdi2 cause shedding of cells from the primary tumor mass into the CSF by increasing cell motility and invasiveness." (PMID 25059231, 2014). "Although Arnt and Gdi2 have previously been implicated in cancer biology, the molecular mechanisms by which these proteins cause medulloblastoma cells to disseminate remain uncertain." (PMID 25059231, 2014). "We asked whether increased expression of ARNT and GDI2 was associated with an increased risk of metastasis in medulloblastoma patients." (PMID 25059231, 2014). "Accordingly, we observed in mouse medulloblastomas induced by Shh + Arnt and Shh + Gdi2 that tumor cells had spread outside the cerebellum to the leptomeningeal surfaces of the brain stem and subependymal spaces of the lateral ventricles." (PMID 25059231, 2014). "Gdi2 had these same effects on tumor precursors and simulated invasiveness in fully transformed medulloblastoma cells." (PMID 25059231, 2014). "We demonstrated the LMD-inducing effects of Arnt and Gdi2 in Shh-induced medulloblastomas in vivo and validated these effects in culture using cell lines in which the Shh signaling pathway is active." (PMID 25059231, 2014). "We analyzed two genes that were sites of frequent transposon insertion and highly expressed in human medulloblastomas: Arnt (aryl hydrocarbon receptor nuclear translocator) and Gdi2 (GDP dissociation inhibitor 2)." (PMID 25059231, 2014). "Here we show that ectopic expression of Arnt and Gdi2 promoted LMD in mice bearing Sonic hedgehog (Shh)-induced medulloblastomas." (PMID 25059231, 2014). "Therefore, we cannot conclude that Arnt and Gdi2 are LMD drivers in Shh-independent medulloblastomas even though Arnt and Gdi2 are expressed in all subgroups." (PMID 25059231, 2014). "Arnt and Gdi2 emerged as candidate LMD-inducing genes from a study in which SB transposon mobilization in Math1+ GNPs in Patched+/− mice caused the typically localized, Shh-driven medulloblastomas to disseminate widely throughout the spinal leptomeninges." (PMID 25059231, 2014). "We show here that ectopic expression of Arnt and Gdi2, which were identified in an unbiased genetic screen for metastasis genes using SB transposon mutagenesis, promotes LMD in Shh-induced medulloblastomas in mice." (PMID 25059231, 2014). "Addition of Arnt and Gdi2 did not alter the classical cytoarchitecture of Shh-induced medulloblastomas, which is characterized by densely packed sheets of cells with nuclear molding and scant cytoplasm." (PMID 25059231, 2014). "Likewise, GDI2 was upregulated in anaplastic thyroid cancers (ATC) and might be a genetic driver of metastatic dissemination in sonic hedgehog medulloblastoma." (PMID 34894398, 2021). "Here we show that ectopic expression of Arnt and Gdi2 promotes spinal LMD in mice bearing Shh-induced medulloblastomas and demonstrate the effects of these genes on the motility, invasiveness, and anchorage-independent growth of medulloblastoma tumor cells and precursor cells in culture." (PMID 25059231, 2014).
pancreatic carcinoma (2 papers, 2018 to 2019). "Increased expression of GDI2 has been reported pancreatic carcinoma." (PMID 30517191, 2018).
viral infection (2 papers, 2022 to 2024). "In our results, the impairment of GDI2 enhances cellular susceptibility to viral infections, indicating that GDI2 functions as an antiviral protein." (PMID 39730330, 2024). "Transfection of both wildtype and mutated GDI2 suppressed viral infection; however, only wildtype GDI2 reinstated the enhancing effect of OI on viral infection." (PMID 39730330, 2024). "In summary, our study demonstrates that itaconate derived from neutrophils facilitates viral infection by directly alkylating GDI2 and retaining Rab GTPases within the membrane." (PMID 39730330, 2024). "Knocking down GDI2 promoted viral infection in lung tissues, while also abolished the promotion of VSV and IAV infection caused by OI treatment." (PMID 39730330, 2024).
Alzheimer disease (1 paper, 2024). A progressive, neurodegenerative disease characterized by loss of function and death of nerve cells in several areas of the brain leading to loss of cognitive function such as memory and language. "Most recently, neuron-specific knockout of GDI2 alleviates neurodegeneration and memory loss in the 5xFAD mice model of Alzheimer’s disease, an autoimmune disease, in which the brain’s immune system mistakenly attacks brain cells." (PMID 39831280, 2024). "Furthermore, GDI2’s role in immune responses, particularly during bacterial infections, and its potential therapeutic implications in conditions like Alzheimer’s disease are explored." (PMID 39831280, 2024).
breast invasive carcinoma (1 paper, 2024). "Together, these data provide valuable insights into the differential expression patterns of ITGB6, ERBB2, RAB5A, RAB7A, and GDI2 in breast invasive carcinoma." (PMID 39630893, 2024).
colon cancer (1 paper, 2024). "The expression of GDI2 was greater in tumor tissues of colon cancer patients or rectal cancer patients than in normal tissues (P < 0.05), and it is hypothesized that GDI2 plays an important role in the proliferation and development of human CRC." (PMID 39323841, 2024).
hepatic disease (1 paper, 2021). "Furthermore, since that HCC was mainly progressed from hepatic fibrosis (HF) till liver cirrhosis (LC), the GDI2 might also participate in hepatic disease progression, similar to its role in multiple sclerosis (MS)." (PMID 34894398, 2021).
ovarian carcinoma (1 paper, 2021). A malignant neoplasm originating from the surface ovarian epithelium. "In human ovarian cancer (OC), paclitaxel-resistance and tumor cell-induced fibroblasts were associated with GDI2 up-regulation in OC cells." (PMID 34894398, 2021).
pancreatic adenocarcinoma (1 paper, 2021). "In human pancreatic adenocarcinoma (PAAD), GDI2 was over expressed and co-localized with Hsp90, together with family member Rab-GDI-1, they regulated agonist-induced amylase release in AR42J cells." (PMID 34894398, 2021).
schizophrenia (1 paper, 2016). A major psychotic disorder characterized by abnormalities in the perception or expression of reality. "Although, the Rab GDP dissociation inhibitor beta (GDI2) has not been found to be altered in schizophrenia proteomic studies, the Rab GDP dissociation inhibitor alpha (GDI1) isoform was previously found to be upregulated in samples of ACC and DLPFC of schizophrenia patients." (PMID 26973466, 2016).
thyroid cancer (1 paper, 2024). "In thyroid cancer cells, microRNA-15b-5p can inhibit cell proliferation and invasion by targeting GDI2, which is associated with poor prognosis in thyroid cancer patients and is negatively regulated by miR-15b-5p." (PMID 39323841, 2024).